MIR1305 (microRNA 1305)
Synonyms: hsa-mir-1305; MIRN1305; mir-1305
Gene: MicroRNA gene on chromosome 4 (182,169,293 to 182,169,378, forward strand). Ensembl gene ENSG00000221227.
Diseases named in the same sentence as MIR1305 in open-access papers:
MIR1305 is named in the same sentence as 1 disease in open-access papers, as found by Europe PMC text mining. Sharing a sentence is not in itself a finding about the gene and the disease. The quoted sentences say what the papers report.
ovarian carcinoma (1 paper, 2022). A malignant neoplasm originating from the surface ovarian epithelium. "Of clinical relevance, we found that ovarian cancer patients bearing a low level of MIR1305 and high expression of DIRAS3 have a longer overall survival compared to patients in which the CNV of MIR1305 was unaltered." (PMID 35565270, 2022). "We observed that ovarian cancer patients bearing a shallow deletion of MIR1305 together with high DIRAS3 expression display a significantly better overall survival compared to that observed in the group of patients with no CNV alterations (possibly expressing high MIR1305)." (PMID 35565270, 2022).